GAA (alpha glucosidase)
Diseases named in the same sentence as GAA in open-access papers (continued):
Sharing a sentence is not in itself a finding about the gene and the disease.
genetic disorder (11 papers, 2017 to 2025). "Pompe disease is a rare genetic disorder characterized by a deficiency of acid α-glucosidase (GAA), leading to the accumulation of glycogen in various tissues, especially in skeletal muscles." (PMID 38698877, 2024). "Pompe disease (PD) is a rare genetic disorder caused by mutations in the gene of the enzyme of acid alpha-glucosidase (GAA) responsible for the breakdown of glycogen." (PMID 39684857, 2024). "Profound muscle atrophy is a hallmark of Pompe disease, a rare genetic disorder caused by a deficiency of acid alpha‐glucosidase (GAA), the enzyme that breaks down glycogen to glucose within lysosomes." (PMID 28130275, 2017).
myopathy (11 papers, 2010 to 2025). A disease of the muscle in which the muscle fibers do not function properly. "However, in an animal model of lysosomal storage Pompe disease due to GAA deficiency, the combined deletion of Atg5 worsens the myopathy, though permitting successful enzyme replacement therapy in autophagy deficient skeletal muscles." (PMID 23630012, 2013). "Cardiac involvement was observed in a total of 6 patients: one each for AMPD1, GAA, DYSF, LMNA, and two GNE-myopathies." (PMID 33250842, 2020).
tumor (10 papers, 2010 to 2025). "Alpha‐glucosidase inhibitors can effectively curtail the caloric intake of tumor cells by lowering blood glucose levels, ultimately leading to the destruction of tumor cells." (PMID 40881483, 2025). "By demonstrating that STBD1 and GAA have potential tumor-suppressive functions, we identify the previously uncharacterized connection between glycophagy and tumorigenesis." (PMID 34059679, 2021). "All seven glucose metabolism-related proteins were downregulated in SBP1 induced-tumor tissue, including GAA, GAPDH, ALDH2, Thioredoxin, ENO3, UGDH and Lumican." (PMID 25974208, 2015). "GAA is involved in regulating the autophagic process in tumor cells." (PMID 37628967, 2023). "To further determine whether STBD1 regulates tumor growth via a role in glycophagy, we test another mediator of glycophagy, lysosomal acid α-acid glycosidase (GAA)." (PMID 34059679, 2021). "Among the 17 overexpressed genes, CDX1 (caudal type homeobox 1) had the highest fold difference in tumor versus non-tumor tissues followed by SI (sucrase-isomaltase, aka alpha-glucosidase), KRT16 (keratin 16) and SERPINB5 (serpin peptidase inhibitor, clade B (ovalbumin), member 5)." (PMID 28418924, 2017).
infection (5 papers, 2014 to 2025). The state of being infected such as from the introduction of a foreign agent such as serum, vaccine, antigenic substance or organism. "Likewise, the begomoviral (TYLCV) infection of whiteflies was also observed to up-regulate the expression of a gene encoding alpha-glucosidase." (PMID 36267190, 2022). "In this study, the expression of many genes involved in the metabolic pathways of starch and sucrose such as TPS, alpha-glucosidase, and beta-glucosidase genes, was significantly up-regulated in strains S after infection." (PMID 37445981, 2023). "Transcriptome analysis showed that the mRNA expression levels of ACSS1_2 (EC: 6.2.1.1) and GAA (EC: 3.2.1.20) were significantly decreased, whereas PYG (EC: 2.4.1.1) markedly increased in the liver after infection." (PMID 40563315, 2025). "The specific genes in the geneset that associated with the greatest odds of reduced risk of infection including SEMA4A, CTSD, CD68, and GAA were all members of this pathway, but not TNFSF13 (APRIL) which was the most protective gene in the NHP studies." (PMID 34533134, 2021).
neuromuscular disease (4 papers, 2014 to 2024). "Recently, the production of AAV vectors in large scale and the positive results reported in preclinical studies of AAV delivery in neuromuscular diseases encouraged studying the AAV vectors containing muscle-specific expression cassettes for GAA transgene." (PMID 32745073, 2020).
cardiovascular disease (3 papers, 2013 to 2025). "CVD: cardiovascular disease, OHA: oral hypoglycemic agents, α-GI: alpha-glucosidase inhibitor, DPP4-I: inhibitors of type 4 dipeptidyl peptidase.* log-transformed for the statistical analysis." (PMID 29233102, 2017).
neurologic disorders (2 papers, 2013 to 2019). "In addition, voglibose, an alpha-glucosidase inhibitor, prevented PPH by reduced splanchnic blood pooling due to an inhibition of neurotensin release in patients with neurologic disorders." (PMID 30845668, 2019).
gastrointestinal disease (1 paper, 2024). A disease that occurs in the gastrointestinal system, excluding the hepatobiliary system. "However, our research found no causal evidence for the impact of metformin, GLP-1 agonists, SGLT2 inhibitors, DPP 4 inhibitors, insulin and its analogs, thiazolidinediones, or alpha-glucosidase inhibitors on gastrointestinal diseases." (PMID 38918852, 2024). "Our study investigated the causal relationship of seven common antidiabetic drug targets–metformin, GLP-1 receptor agonists, SGLT2 inhibitors, DPP-4 inhibitors, insulin and its analogs, thiazolidinediones, sulfonylureas and alpha-glucosidase inhibitors–on various gastrointestinal diseases." (PMID 38918852, 2024).
GAA also shares sentences with these, for which no sentence is quoted: dyslipidemia (6 papers); Hypertension (5); Fabry disease (3); inflammatory bowel disease (3); McArdle disease (3); neuropathy (3); retinopathy (3); COVID-19 (2); cystic fibrosis (2); Hypercholesterolemia (2); liver cancer (2); liver cirrhosis (2); muscle disorders (2); muscular dystrophy (2); prediabetes (2); sphingolipidoses (2); spinal muscular atrophy (2); Stroke (2); 21-hydroxylase deficiency (1); abdominal abscess (1); Alstrom syndrome (1); Angelman syndrome (1); appendicular ataxia (1); argininosuccinic aciduria (1); asthma (1); atherosclerosis (1); autosomal dominant polycystic kidney disease (1); biotinidase deficiency (1); bowel obstruction (1); cardiac hypertrophy (1).
A further 69 diseases each share a sentence with GAA in 1 paper.